KEAP1 (kelch like ECH associated protein 1)
Diseases named in the same sentence as KEAP1 in open-access papers (continued):
Sharing a sentence is not in itself a finding about the gene and the disease.
tumor (continued). "CDKN2A/B co‐mutations were significantly represented in tumours with STK11 (63%, 10/16, p = 0.024), KEAP1 (59%, 10/17, p = 0.045), and SPEN (90%, 9/10, p < 0.001) alterations, and in all tumours with MTAP alterations (100%, 16/16, p < 0.001)." (PMID 41015991, 2025). "Mixed-effects modeling of tumor volumes over time showed that conditional Keap1 KO mice were largely resistant to therapy, whereas conditional Nrf2 KO mice displayed a trend towards improved tumor control." (PMID 41176316, 2025). "ADAR1 predominantly functions as a proto-oncogene, enhancing tumor cell survival under oxidative stress and contributing to poor prognosis through modulation of the Keap1/Nrf2 axis." (PMID 40852728, 2025). "Sequencing data for chromosome 19p (Chr 19p), where the KEAP1 gene is located, showed copy neutral loss of heterozygosity (CN‐LOH) in the PTC tumor component, associated with duplication of the mutant KEAP1 allele and loss of the normal allele." (PMID 40600748, 2025). "Co‐occurring alterations with KRAS included FLT1 (28%, 9/32, p = 0.033), APC (16%, 5/32, p = 0.015), and KEAP1 (16%, 5/32), with four of these tumours also harbouring STK11 alterations, forming a KRAS‐KEAP1‐STK11 mutational profile (13%, 4/32)." (PMID 41015991, 2025). "Nrf2 maintains redox homeostasis through antioxidant gene activation while paradoxically promoting tumor survival and drug resistance via Keap1-dependent degradation and phosphorylation-mediated stabilization." (PMID 40549063, 2025). "We seeded equal numbers of tumor cells and macrophages (WT or Keap1 KO) in ultra-low-adherence plates to form multicellular spheroids." (PMID 41176316, 2025). "Another important pathway which essentially contributes to cellular resistance of tumor cells towards oxidative stress is the Kelch-like epichlorohydrin related protein-1 (Keap1)-nuclear respiratory factor (Nrf2) signaling pathway." (PMID 39851496, 2025). "We further assessed the composition of tumor infiltrating immune cells, assessing which types of immune cells are decreased or increased within the KEAP1-KO 3LL engrafted tumors." (PMID 41035689, 2025). "KEAP1, as a critical component of the ubiquitin ligase complex, exerts tumor‐suppressive effects by promoting NRF2 protein degradation." (PMID 40919133, 2025). "Immunohistochemical analysis revealed that NQO1 protein was expressed at a higher level in the tumor area of the KEAP1-KO tumor tissues than that of the WT tumor tissues." (PMID 41035689, 2025). "A subcutaneous xenograft tumor model was used to further investigate the impact of SLC25A10/p62/KEAP1/Nrf2 on tumor growth in vivo." (PMID 40393974, 2025). "We then aimed to corroborate these findings and further characterize the functionality of T cells within the tumor microenvironment of Keap1 mutant lung tumors treated with DRP-104." (PMID 38536921, 2024). "Given the significance of PD-L1 as a target for tumor immunotherapy, we aimed to investigate the potential involvement of KEAP1 in tumor immunity." (PMID 38413563, 2024). "In summary, our study identifies KEAP1 as a pivotal regulator of PD-L1, holding important implications for anti-tumor immunity." (PMID 38413563, 2024). "To further explore the possibility that circKEAP1 functions as a tumor suppressor in OS partly dependent on KEAP1-259aa, we restored KEAP1-259aa expression in stable circKEAP1 knockdown OS cells." (PMID 38383479, 2024).
tumor (continued). "Results from viability assays and measurements of BCL2 and caspase 3 in the H69V cell line suggest that KEAP1 silencing effectively affects the drug response, with contrasting effects on tumor cells when the two drugs were used separately." (PMID 38791966, 2024). "The results showed that compared to the control group, sh-Keap1-intervened mice exhibited increased tumor volume and weight, while the BA/DDP combination and the DDP/DTX combination exerted protective effects." (PMID 39061086, 2024). "Initial studies by Kadara and others suggest that tumors with Keap1 mutations show increased numbers of CD57+ and granzyme B+ cells around the tumor, indicating enhanced NK cell presence." (PMID 39286246, 2024). "Loss-of-function mutations in KEAP1, which account for approximately 20% of KRAS-mutant NSCLC cases, lead to NRF2 activation, resulting in accelerated tumor growth and chemoresistance." (PMID 39037971, 2024). "Further using this model, we transplanted Keap1 R470C mutant or Keap1 WT KP tumor cells, each expressing luciferase, and continuously tracked the lung tumor burden through bioluminescence imaging." (PMID 38536921, 2024). "We performed multi-color flow cytometry on Keap1 R470C mutant KP tumor-bearing lungs (gating shown in fig." (PMID 38536921, 2024). "miR-141-3p has been reported to have a role in promoting tumor progression in a variety of tumors, while miR-141-3p has been reported to have the ability to regulate Keap1-Nrf2 23-25." (PMID 39308683, 2024). "Moreover, alteration of the Kelch-like ECH-associated protein 1/nuclear factor erythroid 2–related factor 2 (Keap1/Nrf2) pathway, a major regulator of cytoprotective responses to oxidative that continuously targets Nrf2 for proteasome degradation, is also associated with tumor progression." (PMID 39611159, 2024). "This study uncovered a novel KEAP1 anti-tumor mechanism in NSCLC by orchestrating the degradation of PD-L1." (PMID 38413563, 2024). "The KEAP1 fragment was successfully amplified in 23 (82.1%) and in 19 (67.9%) surrounding and tumour tissue samples, respectively." (PMID 39001473, 2024). "Our findings robustly established that KEAP1 ubiquitinates PD-L1 for degradation, influencing tumor progression." (PMID 38413563, 2024). "Some groups have shown the effects of phytocompounds, such as sulforaphane and luteolin, on the methylation status of NFE2L2/KEAP-1 promoters, thereby influencing cell survival and tumor progression in different cancer entities." (PMID 38666930, 2024). "Knockdown of KEAP1 led to enhanced tumor development, whereas the introduction of PD-L1-targeting shRNA significantly mitigated the tumorigenic tendency." (PMID 38413563, 2024). "Macrophages were present in the KEAP1-mutant tumor model (Keap1470C) at a frequency nearly double that of Keap1WT tumors (25.9% vs. 13.5%)." (PMID 38542481, 2024). "We have demonstrated that KEAP1 reduces PD-L1 stability by facilitating ubiquitin-mediated degradation, leading to the inhibition of tumor growth both in vivo and in vitro." (PMID 38413563, 2024). "We recently published a transcriptomic 46-gene signature, the K1N2 score, that robustly predicted KEAP1/NFE2L2 mutation status but also outperformed mutation testing with respect to survival and tumor hypoxia prediction." (PMID 39528799, 2024). "Alterations in several tumor genes, such as mutations in KRAS, STK11, and KEAP1, have been suggested as potential biomarkers for the ICI response in patients with NSCLC." (PMID 39037971, 2024).
tumor (continued). "This complex of nanoparticles selectively accumulates in tumor sites, triggering ferroptosis by inducing ROS production and regulating the expression of KEAP1, NRF2, and HMOX1, which in turn elevates the labile iron pool in 4T1 tumor-bearing BALB/c model mice." (PMID 38962305, 2024). "As expected, the reduction in PD-L1 expression in KEAP1-overexpressing cells led to an upregulation of tumor immunity, evidenced by elevated levels of total and activated CD8+ cytotoxic T cells (GzmB+) within tumor-infiltrating lymphocytes." (PMID 38413563, 2024). "To validate KEAP1’s regulation of NRF2 pathway in LUAD tumor, we curated a NRF2 target gene list by integrating results from 3 independent studies." (PMID 38241355, 2024). "DDW controls the level of oxidative stress by controlling the expression of oxidative genes and antioxidant genes in the Keap1-Nrf2 signalling pathway, further inhibiting tumours." (PMID 38732643, 2024). "We found that overexpression of KEAP1 suppressed tumor growth and promoted cytotoxic T-cell activation in vivo." (PMID 38413563, 2024). "The difference of overall survival rate between high and low neutrophil by set cutoff value as median in tumor immune microenvironment in different groups including LUADs, KEAP1 wt and KEAP1 mt groups were analysed." (PMID 38962454, 2024). "For instance, sulforaphane demonstrates anti-tumor properties by regulating several signaling pathways, such as Nrf2/Keap1, AKT1/HK2, and NF-κB/MMP-9." (PMID 38612546, 2024). "hsa-piR-1089 promoted tumor progression by downregulating the expression of KEAP1 – a tumor suppressor in NB." (PMID 38660306, 2024). "Tumour cells can positively regulate the KEAP1/NRF2 pathway, a key pathway for sensing and responding to oxidative stress." (PMID 39594467, 2024). "Across a range of genetically engineered, patient-derived and orthoptic NSCLC models, [18F]FSPG retention increased in tumours with NRF2 activation compared to those with a normal-functioning NRF2/KEAP1 axis." (PMID 39690148, 2024). "The study has discovered that oxidative damage increased the Keap1 mRNA expression and attenuated the Nrf2 expression in mouse tumor tissues." (PMID 39595285, 2024). "Collectively, miR-141-3p contributes to tumor progression, migration, and M2 polarization of OC by activating the Keap1-Nrf2 pathway." (PMID 37333452, 2023). "Inactivating mutations of KEAP1 led to NRF2 accumulation and hyperactivation of NRF2 target genes that promoted tumor cell growth." (PMID 37660919, 2023). "A similar phenomenon (the appearance of the alternative splicing of Nrf2 without a region corresponding to exon 2 and, therefore, incapable of interacting with Keap1) occurs in tumor cells." (PMID 37109574, 2023). "The overactivation of the KEAP1/NRF2 signaling pathway in tumor cells is one important reason for the poor efficacy of these drugs." (PMID 36719368, 2023). "In fact, a number of these cullins-associated E3 ligases, such as Fbxo31, Keap1, DDB2, and the cullins, have been demonstrated to function as tumor suppressors or components of tumor suppressor complexes." (PMID 37943017, 2023). "Activation of the KEAP1/NRF2/miR-34a/b/c axis mediates the tumor suppressive activity of curcumin and suggests a new approach for activating miR-34 genes in tumors for therapeutic purposes." (PMID 37210578, 2023). "We injected GFP-MC38 tumor cells subcutaneously into both flanks of WT mice and those with conditional Keap1 KO in leukocytes." (PMID 38060331, 2023). "The authors found that the Keap1 tumour to normal tissue ratios was predictive of lympho-vascular invasion, which in turn was a significant predictor of metastasis in these patients." (PMID 36701089, 2023).
tumor (continued). "Keap1 (KLHL19) and three other members of the KLHL family are linked to tumor genesis: KLHL6, KLHL20, and KLHL37 (ENC1)." (PMID 37109574, 2023). "Co-mutations in the tumor suppressors CDKN2A and KEAP1 occur more commonly in patients with KRASG12C-mutated tumors showing intrinsic resistance to adagrasib and/or sotorasib." (PMID 38106234, 2023). "In a study comparing normal and tumour tissues of colorectal cancer patients, Nrf-2 and Keap1 protein levels and their tumour to normal tissue ratios were correlated with the lymph node/distant metastasis status." (PMID 36701089, 2023). "As the KEAP1-NRF2 pathway was found to be highly related to tumor progression, we assessed the impact of KEAP1 SUMOylation on the proliferation of the NSCLC H1299 cell line." (PMID 37660919, 2023). "In a conclusion, our study demonstrates that miR-141-3p is upregulated in OC patients and targets Keap1 to increase the expression of Nrf2, which promotes M2 transformation and boosts the tumor progression." (PMID 37333452, 2023). "Across a range of genetically engineered, patient-derived, and orthoptic NSCLC models, [18F]FSPG retention was increased in tumours with NRF2 activation compared to tumours with a normal-functioning NRF2/KEAP1 axis." (PMID 38168428, 2023). "The co-inactivation of LKB1 and KEAP1 cooperatively promotes metabolic reprogramming in KRAS-mutant tumor, and even in the presence of KEAP1 inactivation, LKB1 inactivation modulates NRF2 activity through increased ROS levels." (PMID 37675220, 2023). "This study showed that parthenolide can differently modify the redox state of KEAP1 in tumor and normal prostate cells suggesting a possible use of this compound as tumor-specific radiosensitizing agent with radioprotective properties in normal cells." (PMID 37296999, 2023). "We previously reported that Nrf2 and the Nrf2-regulated gene Nqo1 are downregulated in high-grade tumours that arise from Keap1/Nrf2 mutant models." (PMID 38168428, 2023). "Once the KEAP1/NFE2L2 pathway is inappropriately active in tumor cells, it can stimulate tumor growth." (PMID 37794491, 2023). "Somatic mutations of NFE2L2 and KEAP1 are one of the main causes of constitutive NRF2 activation, but their frequency varies, importantly, between tumour types." (PMID 37373496, 2023). "Remarkably, loss of KEAP1 completely abrogated the potent response to anti-PD1 treatment, measured both by tumor size and mouse survival." (PMID 36864091, 2023). "Two previous studies showed that p62 is subjected to phosphorylation and p62 phosphorylation at S349 contributes to tumor growth through the disruption of the Keap1–Nrf2 complex." (PMID 37081115, 2023). "Curiously, both KEAP1 and STK11 mutations are associated with worse prognosis in tumours harbouring KRAS G12C mutations compared to G12V or G12D." (PMID 36864508, 2023). "In conclusion, high consumption of glycolysis and glutaminolysis in immune-resistant phenotype tumors, such as NSCLC with LKB1 and/or KEAP1 inactivation, not only contribute to tumor aggressiveness but also impede intratumor T-cell function." (PMID 37675220, 2023). "Fumaric acid can stimulate the Keap1/Nrf2 pathway, leading to the upregulation of antioxidant genes and cytoprotective mechanisms, thereby promoting tumour cell survival." (PMID 37631354, 2023). "The NRF2 negative regulator, KEAP1, shows intrinsic variation in expression, leading to tumor heterogeneity and subclonal resistance." (PMID 36864091, 2023). "Taken together, these results establish a central role of the ROS/KEAP1/NRF2/miR-34a/b/c axis in mediating the tumor suppressive effects of curcumin." (PMID 37210578, 2023). "Kelch-like ECH-associated protein 1 (KEAP1) acts as the primary negative regulator of NRF2 and functions as a tumor suppressor." (PMID 37371948, 2023). "When compared with Keap1+/+ cells, the expression of Keap1 was markedly decreased in Keap1−/−-derived tumour tissues, but markedly increased in Keap1β(Keap1Δ1–31)-derived tumour tissues." (PMID 36142252, 2022).
tumor (continued). "The results revealed that when Keap1 is knocked out, the cell proliferation and migration and its tumour xenografts are reduced." (PMID 36142252, 2022). "TRIM25 is considered as a type of oncoprotein that plays a regulatory role in reactive oxygen balance; it also enhances tumor cell proliferation and drug resistance by promoting Keap1 degradation." (PMID 36012594, 2022). "Simultaneously, IHC staining of mouse tumors showed that combination treatment significantly reduced the expression levels of Ki67 and KEAP1 in subcutaneous tumor tissue." (PMID 35453346, 2022). "Further immunohistochemistry of the tumour-repressing marker PTEN revealed significant enhancements of PTEN in Keap1−/− and Keap1β(Keap1Δ1–31) derived xenograft tissues." (PMID 36142252, 2022). "To further examine the nuclear accumulation of Nrf2, we immunoassayed Nrf2 in Keap1 mutant and WT patients’ tumor samples and in two established HNSCC cell lines." (PMID 35945195, 2022). "To get more insight into the Keap1 mutations and resulting chemoresistance through Nrf2 activation, we assessed the effects of siRNA knockdown of Keap1 on the sensitivity of Cal33 tumor cells to cisplatin." (PMID 35945195, 2022). "They showed that xanthine oxidoreductase inhibits liver CSC survival and tumor promotion through interaction with ubiquitin-specific peptidase 15 which promotes deubiquitylation of KEAP1 leading to NRF2 degradation." (PMID 35268568, 2022). "Together, our study demonstrates that KEAP1 deubiquitination by BAP1 is novel tumor suppressive mechanism of LUAD." (PMID 35052618, 2022). "This suggests that complete intact Keap1 promotes tumour growth, but as Keap1 isoforms, Keap1α inhibits tumour growth, whilst Keap1β promotes tumour growth." (PMID 36142252, 2022). "We also detected nuclear Nrf2 localization in parts of Keap1-wild-type tumor tissues but to a lesser extent than Keap1- mutant tissue (part c)." (PMID 35945195, 2022). "In HCC xenograft mouse models, depletion of TRIM25 increases Keap1 and inactivates Nrf2, suppressing tumor growth." (PMID 36552825, 2022). "The staining results showed that some cell necrosis and liquefaction occurred in the tumour tissues formed by Keap1−/−, Keap1-Restored, and Keap1α-Restored cells, respectively." (PMID 36142252, 2022). "We have demonstrated that BAP1 directly binds to, deubiquitinates, and stabilizes KEAP1, exerting tumor suppressive effects in vitro." (PMID 35052618, 2022). "For instance, hypermethylation of the gene promoter in the KEAP1/NRF2 axis has been described in various tumor tissues and is closely related to tumor recurrence and drug resistance." (PMID 35620395, 2022). "What is more, ctDNA genomic alterations such as KEAP1 and PIK3CB were also in accordance with the difference tendency in tumor tissue samples, indicating that the plasma ctDNA can potentially reflect tumor-derived genomic mutation." (PMID 35155229, 2022). "Overall, our findings describe the comprehensive transcriptome of cells within the follicle cell tumor model at the single-cell resolution and identify a previously unappreciated link between Keap1-Nrf2 signaling and cell plasticity at early tumorigenesis." (PMID 36321803, 2022). "We then investigated the therapeutic potential of combining 4-CBA treatment with RT for treating KEAP1 mutant tumor growth." (PMID 35459868, 2022). "This is also confirmed by further supportive experiments, revealing that deletion of Keap1 or Keap1 isoforms (α or β) inhibited tumour cell colony formation in vitro." (PMID 36142252, 2022). "The NRF2/KEAP1 pathway plays a key role in the chemoresistance process of different tumor types and is capable of inhibiting apoptosis, promoting cell proliferation, and chemoresistance." (PMID 35740584, 2022).